CCND1 (cyclin D1)
Diseases named in the same sentence as CCND1 in open-access papers (continued):
Sharing a sentence is not in itself a finding about the gene and the disease.
lung carcinoma (continued). "In conclusion, we demonstrated that ATDC could promote lung cancer proliferation through NF-κB induced up-regulation of cyclin D1 and c-Myc." (PMID 23776433, 2013). "We found that both cyclin D1 and cyclin E could be effectively restored by restitution of p120ctn-1A or p120ctn-3A in p120ctn depleted lung cancer cells." (PMID 22276175, 2012). "However the number of studies, which evaluated correlations between galectin-3 and cyclin D1 expression is limited and we didn't find any studies performed in lung cancer tissue." (PMID 22024187, 2011). "Thus, ourfinding of increased cyclin D1 in Cr(VI) transformed cells was consistentwith the finding in vivo, supporting a crucial role ofcyclin D1 in the development of chromate induced lung cancer." (PMID 21437242, 2011). "However, the reports of natural products targeting cyclin D1 in lung cancer are limited." (PMID 40301461, 2025). "Similarly, MIA-690 counteracted IR-induced phosphorylation of STAT3 and NF-κB, which, in lung cancer, has been linked to the upregulation of COX-2, MMP9, and cyclin D1, factors that contribute to increased cancer cell survival, proliferation, invasion, and EMT." (PMID 40244089, 2025). "Moreover, a remarkable decrease in USP28 and its substrates, such as c-Myc and Cyclin D1, was shown in lung cancer cells treated with SGH, suggesting that the anticancer function of SGH may be mediated by the downregulation of USP28." (PMID 36879346, 2023). "Therefore, CCND1 promotes tumorigenicity and metastasis of lung cancer cells." (PMID 35246017, 2022). "Early work had shown that, miR-545 levels in lung cancer tissues are downregulated and it may act as tumor suppressor sincemiR-545 mimic inhibits the cell cycle in G0/G1 phase by repressing the expression of Cyclin D1 and CDK4 genes." (PMID 36303933, 2022). "A recent study demonstrated that lung cancer cells cultured with fibronectin showed: increasing Erk and Rho pathways activity; activation of protein tyrosine kinase and inhibition of caspase 3; a decrease of cell cycle inhibitor p21 expression; and cell cycle promoter cyclin D1 stimulation." (PMID 35681572, 2022). "In terms of Cyclins being regulated, Cyclin D1 was found to be regulated the most as miR-202, miR-206, miR-15, miR-9-5p, miR-15a, miR-16-5p, miR-193a-3p, miR-193b, miR-186, miR-545 and miR-146a-5p have been demonstrated impacting Cyclin D1 in their tumor suppression mechanism of lung cancers." (PMID 36303933, 2022). "Furthermore, PCNA together with cyclin D1 could be significantly decreased with miR-107 ectopic expression in lung cancer cells and colorectal cancer cells, suggesting that miR-107 was an important regulator of cell proliferation." (PMID 33981849, 2021). "Therefore, Prox1 can regulate the proliferation of lung cancer cells by binding to Cyclin D1." (PMID 34183992, 2021). "Despite current studies pointing to the fact that CCND1 is overexpressed and activated in a variety of cancers, few reports discuss the underlying molecular mechanisms by which CCND1 is regulated or activated in malignant tumors, especially in FGFR1 amplified lung cancer." (PMID 32380883, 2020). "Therefore, cyclin D1 is considered to be a promising target for the treatment of lung cancer." (PMID 31262974, 2019).
lung carcinoma (continued). "It has been demonstrated that curcumin and its analogues increase the expression of FOXO3a in A549 and H460 human lung cancer cells through enhancement of ROS production, subsequently elevating the expression of FOXO3a target genes including p21, p27 and Bim while decreasing the level of cyclin D1." (PMID 31817718, 2019). "We also found that X-ray irradiation up-regulated Dab2 expression in lung cancer cells with hypermethylated Dab2 gene, which lead to increased Axin expression and subsequently decreased expression of β-catenin, as well as Wnt pathway factors including: cyclin D1, MMP-7 and c-myc in LK cells." (PMID 30547821, 2018). "Moreover, we assessed the correlation between CCND1 mRNA and miR-134 expression in 39 lung cancer tissues, and results indicated expression of CCND1 mRNA and miR-134 showed a remarkably inverse correlation as calculated by Pearson correlation (r2=0.2021, P =0.0041)." (PMID 27166267, 2016). "Thus, we next examined cyclin D1 expression in human primary lung tumors (NSCLC) and pair-matched adjacent lung tissues, and our western blot results demonstrated that the expression of cyclin D1 protein was increased in lung cancer tissues compared with normal lung tissues." (PMID 26840018, 2016). "Cyclin D1 is encoded by CCND1 gene, and is an important oncogene that shown strong power of oncogenicity, by promotion of cell growth, migration, invasion and epithelial mesenchymal transition (EMT), as well as inhibition of cell apoptosis in many tumors including lung cancer." (PMID 27166267, 2016). "Therefore, it may be that ATDC accelerates G1/S phase transition and promotes lung cancer cell proliferation by enhancing the expression of cyclin D1 and c-Myc." (PMID 23776433, 2013). "Therefore, there comes the hypothesis that the expression of cyclin D1 in lung cancer cell could impact the survival time of lung cancer patients." (PMID 20704822, 2010). "For example, UBA7 targets key regulatory proteins such as cyclin D1 and PML-RARα for proteasomal degradation, suppressing the growth of human lung cancer cells." (PMID 40158006, 2025). "It was shown that C. gigantea inhibits the growth of human lung cancer cells by downregulating the genes Akt, CDK4, CCND1, and CCND2, which are important for cell cycle arrest in the G1/S phase." (PMID 40142097, 2025). "EGR1 plays an important role in cancer by promoting tumorigenesis through enhanced cyclin D1 expression in prostate cancer and by interacting with vascular endothelial growth factor A (VEGFA) to stimulate angiogenesis in lung cancer." (PMID 41561975, 2025). "This is consistent with previous literature which implicates cyclin D1 downregulation in S phase arrest, including in resveratrol-treated CRC cells and PM2.5-exposed lung carcinoma cells." (PMID 40176890, 2025). "It inhibited cyclin D1 and E1 in lung cancer and CDK4 expression and modulating cyclin D1 in colorectal cancer and hepatoma cancer." (PMID 39835210, 2025). "Its mechanism of action includes modulating USP5 to enhance the ubiquitination of Cyclin D1 (CCND1), leading to a reduction in its expression levels and exhibiting a synergistic effect with paclitaxel in lung cancer treatment." (PMID 40313038, 2025). "Specifically, CUR inhibits STAT3 phosphorylation and activation in lung cancer cells, leading to a 40%–60% reduction in tumor size and a significant decrease in the expression of STAT3 target genes such as cyclin D1, VEGF, MMP2, and MMP9." (PMID 40860906, 2025). "In non-small cell lung carcinoma, piR-651 increased the expression of Cyclin D1 and CDK4 to promote tumor progression, while piR-55490 inhibited cell proliferation in lung cancer cells by targeting the 3′ UTR (untranslated region) of mTOR mRNA." (PMID 41154843, 2025). "Targeted therapeutic strategies aimed at these critical nodes, such as inhibiting CDK4 or cyclin D1 activity or restoring RB1 function, are expected to offer new therapeutic avenues for lung cancer patients." (PMID 40568194, 2025).
lung carcinoma (continued). "METTL7B expression is elevated in lung cancer, and deletion of METTL7B significantly reduces cyclin D1, a key regulator of the G1/S transition, leading to G0/G1 arrest and inhibition of lung cancer proliferation." (PMID 39289775, 2024). "Inhibitors of miR-130b and miR-423-5p suppressed the promotion of lung cancer by TPE-derived exosomes and reduced the expression of p65 and cyclin D1." (PMID 39337604, 2024). "The translational efficiency of VRK1 mRNA is increased by its binding to the 3’-untranslated region of hnRNPA1, and thus potentiates the expression of CCND1 (cyclin D1) mediated by phosphorylation of CREB, which promotes lung cancer tumor cell proliferation." (PMID 38753965, 2024). "Over-expression of cyclin D1 at mRNA and protein levels after SFN exposure was also observed in lung cancer cells and its expression level was crucial for SFN-induced necrosis/apoptosis." (PMID 38977944, 2024). "Concerning the antitumor effects, the overexpression of Sharp1 inhibited the formation of colonies of lung cancer cells (A549, NCI-H520, and NCI-H596 cells) by promoting a decrease in cyclin D1 (CCND1) expression." (PMID 38067152, 2023). "Our study revealed that treatment of A549 human lung cancer cell line with ALUP, BA and LUP significantly increased the expression of let-7 miRNA and reduced the expression of Cyclin D1, KRAS and VEGF levels." (PMID 37845669, 2023). "Such a scenario has also been reported for other cancer cell models, for instance, in A549 lung cancer cells, where the KD of TRPC1 decreased the protein expression of Cyclin D1 and D3, leading to an increased number of cells in the G1 phase." (PMID 35887266, 2022). "The result showed that the correlation coefficient between STIL and CCND1 was − 0.217, suggesting the strong correlation of STIL and FOXM1 is unique in lung cancer." (PMID 35365182, 2022). "miRNA-545-3p has been reported to induce cell cycle arrest and apoptosis in lung cancer by regulating CDK4 and cyclin D1." (PMID 35260044, 2022). "In agreement with that, through targeting p21 and cyclin D1, curcumin increased the sensitivity to CDDP and inhibited metastasis and cancer progression in lung cancer cell lines, A549 and H2170." (PMID 36500446, 2022). "We found increased mRNA levels of p21 and a significant decrease in cell cycle-promoting proteins such as CDK2, CDK4, cyclin E1, and cyclin D1, suggesting a possible tumor-suppressing role of LCK in liver and lung cancers." (PMID 36430477, 2022). "In recent in vitro studies, PD has been found to hamper lung cancer cell (A549 and NCI-H1975 cells) progression by decreasing cyclin D1 levels and arresting cells at the S phase." (PMID 36364001, 2022). "For example, UBE1L targets cyclin D1 and PML-RARα for proteasomal degradation, suppressing the growth of human lung cancer cells." (PMID 35159348, 2022). "Human A549 and H460 lung cancer cells treated with UA exhibited reduced proliferation, as well as reduced CDK4, cyclin D1 and cyclin E protein and mRNA levels, whereas the levels of p21 and p27 tumor suppressor proteins were increased." (PMID 36364289, 2022). "In the current work, we demonstrated that BHGJT inhibited lung cancer growth by inducing cell cycle arrest via the downregulation of CDK4 and Cyclin D1 and apoptosis via the AKT/GSK3β/β-catenin signaling pathways." (PMID 34659548, 2021). "To gain first insights into the working mechanism of KJ-Pyr-9-induced survival decrease in MYC expressing lung cancer cells, we tested for alterations in mRNA levels of several known MYC target genes, such as CCND1, CCND3, and MYC itself." (PMID 33925297, 2021).
lung carcinoma (continued). "Wei et.al demonstrated that overexpression of BTG2 inhibits the protein expression of cyclin D1, MMP-1, and MMP-2, and inhibit the growth, proliferation, and invasiveness of the A549 human lung cancer cell line." (PMID 34861847, 2021). "All data together indicated that the downregulation of c-Myc, HK2, PKM2, LDHA, PHGDH, PSAT1, cyclin D1, and CDK6 in lung cancer cells was related to the ubiquitin-protein degradation pathway, which was the result that the USP28 was inhibited by SGH." (PMID 33572615, 2021). "In vitro, leptin significantly increased the viability of lung cancer cell lines A549 and H460 in a dose-dependent manner by activation of STAT3, Bcl-2, and cyclin D1." (PMID 33708630, 2021). "We have previously shown that Anthos favorably modulate targets such as β-catenin, cyclin D1, cyclin B1, pERK, VEGF proteins, c-myc and MMP9 in lung cancer H1299 cells." (PMID 34926717, 2021). "Furthermore, we revealed that the β-catenin target gene Cyclin D1 is an essential downstream effector that mediates the biological effects of Cyclin K, implying that the Cyclin K/β-catenin/Cyclin D1 pathway represents a potential therapeutic target in lung cancer." (PMID 33042275, 2020). "Suppression of CTNNB1 downregulates its downstream transcriptional targets (c-Myc, Cyclin D1, and CDK4) and suppresses the proliferation of lung cancer cells." (PMID 33268793, 2020). "In addition, RPE significantly reduced the expression of the oncogenes cyclin D1 and c-myc, which are closely associated with proliferation, while significantly increasing the expression of the oncogene repressor PTEN in both A549 lung cancer cells and HCT116 colorectal cancer cells." (PMID 33158043, 2020). "In network analysis, the hub targets of cinobufotalin injection against lung cancer were identified as VEGFA, EGFR, CCND1, CASP3, and AKT1." (PMID 32148531, 2020). "Inhibition of Cyclin K with siRNA significantly reduced basal expression levels of Cyclin D1 and GNG3, while increasing expression levels of PCDH9, WNT9A and GNG7 in two different lung cancer cell lines." (PMID 33042275, 2020). "As expected, decreases in cyclin D1 and CDK4 were found in the lung cancer cells after the tetracenomycin X treatment." (PMID 30669360, 2019). "For lung cancer, it was shown that the methylation levels of HOXA9, KRTAP8-1, CCND1, and TULP2 have great potential for the early recognition of LUAD in the undetermined lung nodules." (PMID 31850197, 2019). "In addition, the expression of C-MYC, Cyclin D1, Bcl-2, Bcl-xL, COX-2, TWIST1, and MMP2, which are associated with NF-κB signaling, was analyzed to better understand the NF-κB pathways involved in inhibiting lung cancers and was obviously decreased by 160 μM EGCG." (PMID 31777584, 2019). "Doses of tetracenomycin X at 2.5 and 5 μmol/L abated the levels of cyclin D1 and CDK4 (cyclin-dependent kinase 4) in the five lung cancer cells." (PMID 30669360, 2019). "In several cancers, including colorectal cancer, prostate cancer, esophageal cancer, lung cancer and gastric cancer, lncRNA SNHG7 has been known as a potent oncogene by targeting GALNT1, Cyclin D1, FAIM2, p15 and p16." (PMID 30853913, 2019). "Taken together, we demonstrate that miR-193b is a new dual-strand tumor suppressing miRNA and their common target genes (i.e., CCND1, AJUBA, and HEG1) are potential targets for the treatment of lung cancer." (PMID 31262974, 2019). "In lung cancer PAX6 knockdown cell lines, cyclin D1 is suppressed, indicating that PAX6 promote cell cycle transition from G1 to S-phase." (PMID 29716531, 2018). "Real-time PCR and Western blot analysis revealed that silencing PLPP4 repressed the mRNA and protein expression levels of critical cell cycle regulators of the G1/S checkpoint CCND1, CCNA2 and CCNB1 in lung carcinoma cells." (PMID 28851360, 2017).
lung carcinoma (continued). "Our prior work found that USP18 affected stability of cyclin D1 and KRAS, proteins that are overexpressed or constitutively activated in lung cancer cases [19 and LM Mustachio personal communication]." (PMID 27980214, 2017). "Here, we reported that miR-134 is indeed suppressed in primary lung cancers compared with the matching adjacent normal tissues, and found 3′-UTR of the human CCND1 mRNA is really a target of miR-134." (PMID 27166267, 2016). "The protein expression levels of cyclin D1 and Cdc2 were also significantly decreased after TOPK silencing in lung cancer cells exposed to EGF." (PMID 26745678, 2016). "The protein expression of several cyclins including cyclin A2, cyclin B1, cyclin D1, and cyclin E2 was markedly suppressed by GSK-3α knockdown in lung cancer cell lines." (PMID 27049759, 2016). "Here, we reported that miR-326 is indeed suppressed in primary lung cancers compared with the matching adjacent normal tissues, and found 3′-UTR of the human CCND1 mRNA is really a target of miR-326." (PMID 26840018, 2016). "Catechol attenuated the expression of CDK2 and CDK4 and their respective regulatory partners, cyclin E and cyclin D1 in a dose-dependent manner in KP2 and H460 lung cancer cells." (PMID 27167001, 2016). "Using siRNA knockdown, we confirmed that JunD downregulation decreased expression of cyclin D1, cyclin E and MMP9 in lung cancer cells." (PMID 27184257, 2016). "In both these two lung cancer cell lines, ART, DHA, and ARTS suppressed the proliferation of tumor cells by arresting their cycle in G1 phase and simultaneously decreasing cyclin D1 expression." (PMID 27119499, 2016). "Downregulation of ILK expression and CDDP treatment, in combination, is a more effective approach for the treatment of lung cancer through affecting downstream gene expression, including p-GSK3β, p-AKT, AP-1, β-catenin, cyclin D1 and MMP-9." (PMID 25760437, 2015). "In lung cancer cells CL3, Ape1 redox activity facilitated the cyclin D1 expression and G1 to S progression following ERK activation." (PMID 26639148, 2015). "Previous studies report that the expression of cyclin D1 and CDK4 in human lung cancer tissues is substantially higher than that in normal lung tissues." (PMID 24505359, 2014). "We found that miR-545 suppresses cell proliferation by directly targeting cyclin D1 and CDK4 genes in lung cancer cell lines." (PMID 24505359, 2014). "Knockdown of ATDC reduced the protein levels of cyclin D1, p-Rb, CDK4, CDK6 and c-Myc in the 2 lung cancer cell lines with endogenous expression of ATDC." (PMID 23776433, 2013). "To investigate the mechanism of cell cycle progression regulated by ATDC in lung cancer, we examined the effect of ATDC on cyclin A, cyclin D1, cyclin E, CDK2, CDK4, CDK6, p-Rb and c-Myc in lung cancer cell lines." (PMID 23776433, 2013). "TRIM24 was found to be overexpressed in 81 of 113 (71.7%) human lung cancer samples and correlated with p-TNM stage (p = 0.0006), poor differentiation (p = 0.004), Ki67 index (p<0.0001), cyclin D1(p = 0.0096) and p-Rb expression (p = 0.0318)." (PMID 22666376, 2012). "Data obtained from microarrays, tissue samples from lung cancer patients and human lung cancer cell lines indicate that cell cycle regulatory molecules, like E2F1–5, p130, Skp2, cyclin D1 and p16, contribute to the growth and progression of lung tumors." (PMID 20421925, 2010). "This study was carried out to examine cyclin D1 (CCND1) and retinoblastoma (RB1) gene expression in the bronchial epithelium of patients with lung cancer." (PMID 9192978, 1997). "Interestingly, CDX2 was found to inhibit Wnt signaling in lung cancer cells via suppression of c-MYC, cyclin D1 and survivin expression." (PMID 40002854, 2025). "In addition, CFIm25 depletion in lung cancer cells decreased CCND1 distal PAS usage and enhanced cyclin D1 levels and cell proliferation." (PMID 40022203, 2025).